MYCN (MYCN proto-oncogene, bHLH transcription factor)
Diseases named in the same sentence as MYCN in open-access papers (continued):
Sharing a sentence is not in itself a finding about the gene and the disease.
retinoblastoma (103 papers, 2002 to 2026). A malignant tumor that originates in the nuclear layer of the retina. "The tumor cells displayed marked nuclear enlargement and pleomorphism, closely resembling the hallmark pathological features of clinical MYCN-amplified retinoblastoma." (PMID 40943594, 2025). "In this study, we successfully established a novel human retinal organoid model of MYCN-driven retinoblastoma, demonstrating peak susceptibility to MYCN-mediated tumorigenesis within the developmental window of 70–120 days." (PMID 40943594, 2025). "Intriguingly, retinoblastoma only develops in mice when overexpressed MYCN collaborates with pRB loss in retinal cells." (PMID 39000021, 2024). "MYCN knockdown in our cell models caused a partial growth arrest and reactivated the photoreceptor gene signature of subtype 1 retinoblastoma in the subtype 2 cell lines." (PMID 39079981, 2024). "Knockdown of MYCN expression in retinoblastoma cell models causes growth arrest and reactivates a subtype 1-specific photoreceptor signature." (PMID 39079981, 2024). "MYCN overexpression is associated with increased malignancy in numerous tumor types and amplification of this oncogene is one of the most often events in retinoblastoma." (PMID 38332874, 2024). "MYCN-amplified retinoblastomas exhibit distinct gene signatures associated with MYCN overexpression, acting as the primary driver in this rare and aggressive subtype." (PMID 39000021, 2024). "Copy-number amplifying mutations of the MYCN gene (MYCNA) causing MYCN over-expression have been found in retinoblastomas." (PMID 35729105, 2022). "To mimic MYCN over-expression after copy number MYCN-mutations in retinoblastoma, we used the genome-integrating piggyBac expression system to generate stable and cell-ubiquitous expression of human MYC-sequences in chicken retinal cells." (PMID 35729105, 2022). "Retinoblastoma (Rb) is a childhood cancer of the developing retina caused by biallelic inactivation of RB1 or MYCN amplification in a susceptible retinal cell type." (PMID 34003213, 2021). "SCNAs were found in two-thirds of aqueous humour samples, 80% of which were SCNAs previously shown to be highly recurrent in retinoblastoma tumours, namely gains of 1q, 2p (including focal MYCN amplification), and 6p or a loss of 13q or 16q." (PMID 33805427, 2021). "It was originally believed that profound amplification of MYCN (≥10 copies) was only associated with a small subset of retinoblastomas that lack detectable RB1 mutations." (PMID 33670346, 2021). "In fact, retinoblastoma forms when the effect of overexpressed MYCN cooperates with pRb loss in mouse retinal cells." (PMID 32824373, 2020). "We analyzed a transcriptome of MYCN-amplified retinoblastoma cells deficient for MYCNOS1 and, finally, tested the responses of these cells to chemotherapeutic agents." (PMID 33270844, 2020). "Our findings indicate that MYCNOS coding for MYCNOS1 has a pathogenic consequence of MYCN amplification in MYCN-driven retinoblastoma." (PMID 33270844, 2020). "The profiles of MYCNOS variants and MYCN status were determined in 17 retinoblastoma tissues, cell lines, retinas, and retinal organoids." (PMID 33270844, 2020). "We analyzed the mutation status of the RB1 gene and MYCN copy number in a series of 245 unilateral retinoblastomas, and the phosphorylation status of pRb in a subset of five tumors using immunohistochemistry." (PMID 28211617, 2017). "Consistent with this, FANCA expression is up-regulated in basal breast tumors compared with non-basal breast tumors, and has higher expression levels in RB1-mutated retinoblastomas than MYCN-amplified retinoblastomas." (PMID 28239445, 2017). "To define which of the identified mechanisms is present in MYCN‐amplified retinoblastoma, we first investigated MYCN copy number and the mutations present in RB1 in a series of 245 cases of unilateral retinoblastoma." (PMID 28211617, 2017).
retinoblastoma (continued). "The functional significance of BCOR mutations or MYCN amplifications is yet to be established in vivo in human retinoblastoma." (PMID 23765217, 2013). "Importantly, we observed a stark difference in drug sensitivity between MYCNO/E-cells and the classical RB1-deficient retinoblastoma cell line Y79, despite the latter carrying secondary MYCN amplification." (PMID 40943594, 2025). "In contrast, MYCN-amplified retinoblastoma usually lacks RB1 mutations entirely." (PMID 41009976, 2025). "As MYCN is required for the proliferative response to pRB loss and triggers retinoblastoma when amplified and overexpressed, these findings suggest that increased MYCN RNA expression and regulon activity contribute to pRB-deficient cone precursor proliferation and retinoblastoma genesis." (PMID 40767624, 2025). "There is a need to study whether altered MYCN expression in human retinoblastoma samples correlates with any of the high-risk histological factors." (PMID 34680394, 2021). "As a consequence, it was suggested that MYCN amplifications and RB1 mutations were mutually exclusive and that N-MYC dysregulation could provide an alternative pathway to malignancy in retinoblastomas." (PMID 33670346, 2021). "Whether the use of a PARP inhibitor is effective in treating MYCN mutated retinoblastoma will require further investigation." (PMID 34639028, 2021). "RB1 loss (RB1null) or MYCN amplification (MYCNamp) in fetal human retina causes retinoblastoma." (PMID 32123578, 2020). "Thus, we attempted to identify MYCNOS variants in retinoblastoma and aimed to decipher the role of MYCNOS variant 1 (MYCNOS1) on the activity of MYCN-amplified retinoblastoma." (PMID 33270844, 2020). "Interestingly, MYCN expressing retinoblastomas are larger than RB1-only mutated retinoblastomas of the equivalent age." (PMID 28358317, 2017). "Thus, in conclusion, in our series of 18 MYCN‐amplified retinoblastomas, 12 carry inactivating coding sequence mutations in the RB1 gene and six do not." (PMID 28211617, 2017). "Retinoblastoma is a rare childhood cancer initiated by RB1 mutation or MYCN amplification, while additional alterations may be required for tumor development." (PMID 27126562, 2016). "Examining each question revealed that the greatest increase in score was found in questions related to recent discoveries in retinoblastoma genetics, such as Question 5 which concerns retinoblastoma caused by a rare and only recently appreciated alteration, overexpression of the oncogene MYCN." (PMID 26035834, 2015). "MYCN has been implicated in metastasis in genetically engineered mouse models of retinoblastoma but it is not known if it contributes to progression or metastases in human retinoblastomas." (PMID 24509483, 2014). "MYCN amplification can also occur in more typical retinoblastoma (RB) tumors where the RB1 gene is mutated (RB1−/−), resulting in the loss of functional RB protein." (PMID 40317918, 2025). "Thus, a detailed investigation into how MYCN dysregulates developmental timing and disrupts regulatory networks in the developing human retina is crucial to better understand the early mechanisms underlying retinoblastoma tumorigenesis." (PMID 40943594, 2025). "Although mutations in both RB1 alleles appear to be central to retinoblastoma, a small subset of unilateral tumors lack detectable mutations in this gene; instead, they exhibit significantly increased expression of the n-myc proto-oncogene (MYCN—myelocytomatosis-neuroblastoma)." (PMID 39000021, 2024). "The enrichment of genes associated with MYC-targets might indicate that deregulation of gene expression by MYCN could be an important factor in retinoblastoma development, strengthened by rare retinoblastoma entities in which MYCN amplification substitutes for mutational RB1 inactivation." (PMID 35565295, 2022).
retinoblastoma (continued). "Once this molecular testing method is validated in larger multicenter studies, cell-free DNA analysis of retinoblastoma may allow physicians to precisely identify germline RB1 or MYCN mutations and prepare personalized therapy regimens and family genetic counseling." (PMID 34195690, 2021). "A platform for initiation of retinoblastoma in a developing human retina in vitro would allow unique freedom to test various temporal settings for the mutagenic events e.g. loss of RB1 function on different levels or gain of a MYCN or OTX2 amplification at different steps in retinal development." (PMID 29124525, 2017). "Retinoblastoma (Rb) is an intraocular tumor caused by genetic alterations in the RB1 and MYCN genes within developing retinal cells." (PMID 41898516, 2026). "MYCN-amplified retinoblastoma, though rare, requires early recognition due to its aggressive nature." (PMID 41009976, 2025). "Collectively, these findings highlight a distinct therapeutic sensitivity profile of MYCN-overexpressing retinoblastoma cells, particularly to transcriptional inhibitors (THZ1, Flavopiridol) and the PLK1 inhibitor Volasertib." (PMID 40943594, 2025). "To elucidate the precise developmental context of MYCN-driven retinoblastoma, we utilized a human retinal organoid model to investigate how the timing of MYCN expression influences cellular susceptibility to oncogenic transformation." (PMID 40943594, 2025). "Despite the significant strengths of our retinal organoid model in recapitulating the developmental and molecular features of MYCN-amplified retinoblastoma, several important limitations should be acknowledged." (PMID 40943594, 2025). "In conclusion, this study significantly enhances the understanding of MYCN-amplified retinoblastoma by establishing a robust, human-specific modeling platform—encompassing retinal organoids, derived cell lines, and orthotopic xenografts." (PMID 40943594, 2025). "Transcriptomic profiling demonstrated that MYCN-overexpressing organoids closely recapitulated molecular features of patient-derived MYCN-amplified retinoblastomas, particularly through activation of MYC/E2F and mTORC1 signaling pathways." (PMID 40943594, 2025). "Ultimately, this work establishes a robust platform for future mechanistic studies and the identification of targeted interventions in MYCN-driven retinoblastoma." (PMID 40943594, 2025). "Retinoblastoma protein inactivation leads to MYCN overexpression, resulting in retinoblastoma tumorigenesis and up-regulation of genes that promote the proliferation of retinoblastoma cells in mice." (PMID 39802403, 2025). "The strong concordance between our retinal organoid model and clinical MYCN-amplified retinoblastoma further supports the validity and clinical relevance of our organoid system for investigating MYCN-driven tumor biology." (PMID 40943594, 2025). "This selective sensitivity likely reflects a heightened dependency of these cells on MYC-driven signaling (‘oncogene addiction’), emphasizing the vulnerability of retinoblastoma cells primarily driven by MYCN amplification." (PMID 40943594, 2025). "A central outcome of our study is the refinement of the cellular origin for MYCN-amplified retinoblastoma." (PMID 40943594, 2025). "Based on these features, we designate these transformed models as MYCN overexpressing retinoblastoma organoids (MYCNO/E-RBOs)." (PMID 40943594, 2025). "MYCN-overexpressing retinoblastoma cells (MYCNO/E-cells) demonstrated remarkable sensitivity to MYC-targeting therapies, particularly transcriptional inhibitors such as THZ1 (a selective CDK7 inhibitor) and Flavopiridol (a broader-spectrum CDK inhibitor)." (PMID 40943594, 2025). "These differential drug sensitivities underscore the importance of tailoring therapeutic strategies toward specific oncogenic dependencies in MYCN-driven retinoblastoma." (PMID 40943594, 2025).
retinoblastoma (continued). "Genes involved in protein synthesis appeared to be controlled by MYCN in retinoblastoma, consistent with previous findings in other cancers." (PMID 39079981, 2024). "In retinoblastoma, MYCN amplification occurs in both the more common RB1−/− and rare RB1-proficient backgrounds." (PMID 39079981, 2024). "Taken together, this paper contributes to the understanding of regulatory events in RB1-proficient MYCN-overexpressing retinoblastoma." (PMID 37606819, 2024). "No other transcription factor was more abundant (transcript level) than MYCN in MYCNA retinoblastomas." (PMID 39079981, 2024). "Here we aimed to define the impact of MYCN activity in the context of retinoblastoma subtypes 1 and 2 in a cohort of 61 retinoblastoma samples enriched by six RB1-proficient MYCNA and two extraocular metastatic relapse samples." (PMID 39079981, 2024). "RB1-proficient MYCNA retinoblastomas are currently considered a separate disease entity with very aggressive behavior, in which MYCN is thought to exclusively drive tumorigenesis." (PMID 39079981, 2024). "We also assessed the opposite picture of expression (genes upregulated by MYCN knockdown) from our sleuth-modeled MYCN-knockdown expression profile in the 52 primary retinoblastomas." (PMID 39079981, 2024). "These three tumors were identified as MYCNA, supporting the validity of MYCN-RB signature to identify MYCN-amplified retinoblastomas." (PMID 39079981, 2024). "This subtype 2-MYCN (cluster C) comprises not only the rare RB1-proficient MYCNA retinoblastoma but also RB1−/− retinoblastomas with overactive components of MYCN signaling." (PMID 39079981, 2024). "Our data suggest that de-differentiation from subtype 1 to subtype 2-MYCN (cluster C) retinoblastoma can be reversed by inhibiting MYCN." (PMID 39079981, 2024). "As MYCN amplification alone was insufficient to identify MYCN-driven retinoblastomas, we defined the MYCN-RB signature using data from MYCN-knockdown cell models." (PMID 39079981, 2024). "Using consensus clustering of DNA methylation analysis from 61 retinoblastomas, we identify a MYCN-driven cluster of subtype 2 retinoblastomas characterized by DNA hypomethylation and high expression of genes involved in protein synthesis." (PMID 39079981, 2024). "Here, we first define a MYCN-driven group of subtype 2 retinoblastoma characterized by hypomethylation and high expression of MYCN target genes." (PMID 39079981, 2024). "Our aim was to precisely define the molecular patterns of retinoblastoma with oncogenic MYCN activity within subtype 2." (PMID 39079981, 2024). "In this work we have analysed the transcriptome of established chicken retinoblastoma cells with stable MYCN over-expression (henceforth referred to as “DMC cells”) taken acutely (“young” DMC cells) and after culturing for more than 200 days (“old” DMC cells)." (PMID 37606819, 2024). "This supports the idea of MYCN cooperation with translation processes in retinoblastoma and opens up perspectives for new drug targets in MYCN-driven retinoblastomas." (PMID 39079981, 2024). "RB1-proficient retinoblastoma has been described as a separate retinoblastoma entity with very aggressive behavior, in which MYCN is thought to be the exclusive driver of tumorigenesis." (PMID 39079981, 2024). "In conclusion, with proficient RB1, MYCN-induced high level of E2F expression dysregulates the cell cycle and contributes to retinoblastoma carcinogenesis." (PMID 37606819, 2024). "Here, we investigate the regulatory events in MYCN-induced retinoblastoma carcinogenesis based on the model in chicken." (PMID 37606819, 2024). "In vivo MYCN-transformed chicken retinal cells grow in vitro as aggregates in suspension, similar to the way of established retinoblastoma lines such as WERI-RB1 and Y79." (PMID 37606819, 2024). "MYCN oncogene amplification has been observed in a small subgroup of retinoblastomas grouped into subtype 2 retinoblastoma." (PMID 39079981, 2024).
retinoblastoma (continued). "Our results suggest that bHLH factors, such as MYCN, are highly expressed in cluster C retinoblastoma." (PMID 39079981, 2024). "Over-expression of MYCN in the progenitor cells is sufficient to drive neoplastic growth into retinoblastoma and the resistance to apoptosis in the cone/horizontal cell lineage contributes to the tumorigenic phenotype." (PMID 37606819, 2024). "Several studies in rodent models showed cooperation between MYCN and loss of RB1 in accelerating retinoblastoma formation." (PMID 36982482, 2023). "For instance, a small but significant percentage of retinoblastoma cases are genetically marked by MYCN amplification in a wild-type RB1 background." (PMID 36982482, 2023). "Retinoblastoma makes up for 4% of childhood tumors and is characterized by MYCN amplification and/or overexpression." (PMID 37046804, 2023). "Differential methylation profiling identified a large number of significantly hypomethylated and hypermethylated genes in MYCN-amplified RB1-proficient wild-type tumors compared with MYCN-silent retinoblastomas." (PMID 36245757, 2022). "The expression pattern of these genes clearly separates MYCN-amplified RB1-proficient tumors from other retinoblastomas, observed in both in-house and public-domain patient cohorts." (PMID 36245757, 2022). "The integrated analysis identified 79 overlapping genes that showed hypermethylation on promoter shore or island regions and that were significantly downregulated in MYCNARB1PRO retinoblastomas compared with MYCN-silent retinoblastomas." (PMID 36245757, 2022). "In conclusion, although MYCN-amplified RB1-proficient tumors reside within the molecular spectra of retinoblastoma, they still possess significant differences in expression and methylation patterns that distinguish them from the other retinoblastoma tumors." (PMID 36245757, 2022). "Somatic copy number analysis identified 5 retinoblastoma tumors with high-level MYCN amplification (absolute copy number, > 10)." (PMID 36245757, 2022). "Considerably fewer shelf and open sea hypermethylated genes showed significant downregulation in MYCN-amplified retinoblastomas." (PMID 36245757, 2022). "Data integration identified a 40-gene expression signature with hypermethylated state resulting in a significant downregulation in MYCN-amplified RB1-proficient retinoblastomas." (PMID 36245757, 2022). "MYCN-amplified RB1-proficient retinoblastomas display significantly distinct molecular features compared with other retinoblastomas, including a set of 40 hypermethylation-driven downregulated genes." (PMID 36245757, 2022). "MYCN-amplified RB1-proficient (MYCNARB1+/+) retinoblastomas are diagnosed at an earlier age compared with classic RB1–/– retinoblastomas and display more aggressive clinical behavior." (PMID 36245757, 2022). "Overall, it was shown that the hypermethylation observed in high MYCN-amplified RB1-proficient retinoblastomas has significant influence on global gene expression in this tumor subtype." (PMID 36245757, 2022). "Overall, the results showed that MYCN-amplified RB1-proficient retinoblastomas do possess distinct molecular signatures that diverge them from MYCN-silent or RB1-null retinoblastoma, or both." (PMID 36245757, 2022). "Recent work also showed that MYCN as an oncogene in retinoblastoma modulates several systems that contribute to enhanced viability and invasiveness." (PMID 35729105, 2022). "We showed that genes upregulated in MYCN-amplified RB1-proficient retinoblastomas were significantly enriched for translation and mRNA synthesis processes, whereas downregulated genes were enriched for cell cycle regulation pathways." (PMID 36245757, 2022). "Our results show that MYCN acts as an oncogene in RB1-proficient retinas, leading to neoplasia in two novel models of retinoblastoma: one with MYCN over-expression in the chicken retina and one in hESC-derived retinal organoids." (PMID 35729105, 2022).